MAPK15 (mitogen-activated protein kinase 15)
Description:
Atypical MAPK protein that regulates several process such as autophagy, ciliogenesis, protein trafficking/secretion and genome integrity, in a kinase activity-dependent manner. Controls both, basal and starvation-induced autophagy throught its interaction with GABARAP, MAP1LC3B and GABARAPL1 leading to autophagosome formation, SQSTM1 degradation and reduced MAP1LC3B inhibitory phosphorylation. Regulates primary cilium formation and the localization of ciliary proteins involved in cilium structure, transport, and signaling. Prevents the relocation of the sugar-adding enzymes from the Golgi to the endoplasmic reticulum, thereby restricting the production of sugar-coated proteins. Upon amino-acid starvation, mediates transitional endoplasmic reticulum site disassembly and inhibition of secretion. Binds to chromatin leading to MAPK15 activation and interaction with PCNA, that which protects genomic integrity by inhibiting MDM2-mediated degradation of PCNA. Regulates DA transporter (DAT) activity and protein expression via activation of RhoA. In response to H(2)O(2) treatment phosphorylates ELAVL1, thus preventing it from binding to the PDCD4 3'UTR and rendering the PDCD4 mRNA accessible to miR-21 and leading to its degradation and loss of protein expression. Also functions in a kinase activity-independent manner as a negative regulator of growth (By similarity). Phosphorylates in vitro FOS and MBP. During oocyte maturation, plays a key role in the microtubule organization and meiotic cell cycle progression in oocytes, fertilized eggs, and early embryos (By similarity). Interacts with ESRRA promoting its re-localization from the nucleus to the cytoplasm and then prevents its transcriptional activity.
Synonyms: ERK7; ERK8
Tractability: Small molecule: a high-quality ligand is known; it belongs to a druggable protein family. PROTAC: UniProt records ubiquitination sites on it; a small molecule that binds it is known.
Target class: CMGC protein kinase MAPK family; Protein Kinase; Enzyme; Kinase; CMGC protein kinase group
Gene: Protein-coding gene on chromosome 8 (143,716,279 to 143,722,458, forward strand). Ensembl gene ENSG00000181085.
Subcellular location: Cytoplasm, cytoskeleton, cilium basal body; Cell junction, tight junction; Cytoplasm, cytoskeleton, microtubule organizing center, centrosome, centriole; Cytoplasmic vesicle, autophagosome; Golgi apparatus; Nucleus; Cytoplasm; Cytoplasm, cytoskeleton, spindle
Subcellular location (Human Protein Atlas): Cytosol; Nucleoplasm; Cell Junctions; Vesicles
Gene Ontology:
Molecular function: chromatin binding; kinase activity; MAP kinase activity; protein binding; protein kinase activity; SH3 domain binding; ATP binding; protein serine kinase activity
Biological process: COPII vesicle coating; DNA damage response; dopamine uptake; endoplasmic reticulum organization; negative regulation of cell migration; positive regulation of cell population proliferation; positive regulation of telomere maintenance; positive regulation of transcription by RNA polymerase II; protein autophosphorylation; protein localization to ciliary transition zone; regulation of autophagy; regulation of cilium assembly; intracellular signal transduction; cellular response to stress; MAPK cascade; positive regulation of metaphase/anaphase transition of meiosis I; positive regulation of spindle assembly
Cellular component: autophagosome; axoneme; cell-cell junction; centriole; ciliary basal body; cytoplasm; Golgi apparatus; nucleus; extracellular region; bicellular tight junction; meiotic spindle; spindle
Genetic constraint (gnomAD): Loss-of-function variants: 67 observed, 61.08 expected, observed/expected ratio (o/e) 1.1, 90% interval 0.9 to 1.34. The upper end of that interval is the gene's LOEUF score, 1.34, which puts it in group 5 of 6, group 1 being the genes least tolerant of losing a copy. Missense variants: 808 observed, 738.52 expected, observed/expected ratio (o/e) 1.09, 90% interval 1.03 to 1.16. Synonymous variants: 356 observed, 321.45 expected, observed/expected ratio (o/e) 1.11, 90% interval 1.01 to 1.21.
Homologues: Orthologues: chimpanzee MAPK15 (99% identical), macaque MAPK15 (92% identical), dog MAPK15 (73% identical), mouse Mapk15 (71% identical), pig MAPK15 (70% identical), rat Mapk15 (70% identical), guinea pig MAPK15 (70% identical), rabbit MAPK15 (69% identical), tropical clawed frog mapk15 (49% identical), zebrafish mapk15 (48% identical), Caenorhabditis elegans mapk-15 (42% identical), Drosophila melanogaster Erk7 (37% identical). Paralogues in human: MAPK7 (29% identical), MAPK1 (26% identical), MAPK4 (26% identical), MAPK6 (25% identical), MAPK10 (25% identical), MAPK3 (25% identical), MAPK9 (25% identical), MAPK13 (24% identical), MAPK14 (24% identical), MAPK11 (24% identical), MAPK8 (24% identical), NLK (24% identical), and 7 more.
Diseases named in the same sentence as MAPK15 in open-access papers:
MAPK15 is named in the same sentence as 45 diseases in open-access papers, as found by Europe PMC text mining. Sharing a sentence is not in itself a finding about the gene and the disease. The quoted sentences say what the papers report.
gastric cancer (8 papers, 2015 to 2025). A primary or metastatic malignant neoplasm involving the stomach. "Then, other researchers revealed that MAPK15 in gastric cancer is associated with copy number gain and contributes to the malignant transformation by prolonging the stability of c-Jun." (PMID 38203280, 2023). "Previous research indicates that MAPK15 is involved in the transformation of colon cancer, promotes gastric cancer cell proliferation, and is associated with autophagy." (PMID 36900191, 2023). "Over-expression of MAPK15 is associated with copy number gain and contributes to the c-Jun stability in gastric cancer." (PMID 30524968, 2018). "We further examined the effect of MAPK15 on c-Jun activation in gastric cancer cells to understand the molecular mechanisms underlying G1-S arrest by MAPK15 knockdown." (PMID 26035356, 2015). "Copy number gains or overexpression of MAPK15 in premalignant lesion of gastric mucosa can be a risk factor of gastric cancer." (PMID 26035356, 2015). "To further understand the clinicopathological significance of MAPK15 and the mechanism underlying its oncogenic role in gastric cancer, we analyzed the effect of MAPK15 knockdown or overexpression on cell cycle, c-Jun phosphorylation, and c-Jun stability in gastric cancer cells." (PMID 26035356, 2015). "It has been discovered that MAPK15 overexpression, an oncogene, stimulates the growth of gastric cancer cells by maintaining c-Jun expression." (PMID 39866235, 2025). "MAPK15 has been shown to phosphorylate c‐Jun at these sites in colon cancer, osteosarcoma, and gastric cancer." (PMID 39348153, 2025). "Current research indicates that MAPK15 can promote the transformation of colon cancer by mediating the activation of the transcription factor c-Jun or promoting the growth of gastric cancer cells." (PMID 36900191, 2023). "The overexpression and CNAs of MAPK15 was found in 14 (37%) of 38 formalin-fixed paraffin-embedded tissues and in 15 (17%) of 88 fresh-frozen gastric cancer tissues, respectively." (PMID 26035356, 2015). "The mRNA levels of MAPK15 in gastric cancer were significantly different between tissues with CNAs and those without (P = 0.007)." (PMID 26035356, 2015). "To understand the biological function of MAPK15 in gastric cancer, we analyzed the effects of MAPK15 downregulation on cell proliferation and cell cycle in gastric cancer cells." (PMID 26035356, 2015). "Knockdown of MAPK15 using siRNA in gastric cancer cells significantly suppressed cell proliferation and resulted in cell cycle arrest at G1-S phase." (PMID 26035356, 2015). "Genome-wide copy number alterations (CNAs) were first investigated in 40 gastric cancers using Agilent aCGH-244K or aCGH-400K, and copy number gains of MAPK15 found in aCGH were validated in another set of 48 gastric cancer tissues." (PMID 26035356, 2015). "We first investigated genome-wide copy number alterations (CNAs) in 40 gastric cancers using Agilent aCGH-244K or aCGH-400K and identified copy number gains (20%) on 8q24.3 where MAPK15 is located." (PMID 26035356, 2015). "The mRNA levels of MAPK15 in 48 gastric cancer tissues were detected by qPCR and their associations with copy number were analyzed." (PMID 26035356, 2015). "The mRNA levels of MAPK15 were relatively high in the gastric cancer tissues and gastric cancer cells with higher copy number gains than those without." (PMID 26035356, 2015). "This study was aimed at understanding the functional and clinicopathological significance of MAPK15 alteration in gastric cancer." (PMID 26035356, 2015). "The effects of MAPK15 on cell cycle, c-Jun phosphorylation, and mRNA stability were analyzed in gastric cancer cells." (PMID 26035356, 2015). "We analyzed the expression of MAPK15 in normal, adenoma, and carcinoma tissues derived from the same gastric cancer patients in order to determine the time point of MAPK15 expression during the process of malignant transformation." (PMID 26035356, 2015).
gastric cancer (continued). "Copy number gains of MAPK15 were found in 15 (17%) of 88 gastric cancer tissues and in 7 (44%) of 16 gastric cancer cell lines." (PMID 26035356, 2015). "The expression of MAPK15 was analyzed using immunohistochemistry in concurrent lesions of normal, adenoma, and carcinoma from additional 45 gastric cancer patients." (PMID 26035356, 2015). "Furthermore, aberrant MAPK15 expression has been reported in various cancers, such as breast cancer, lung neuroendocrine neoplasms, and gastric cancers." (PMID 38203280, 2023). "In spite of frequent overexpression of MAPK15 in human cancers, mechanisms underlying the overexpression are not clear in gastric cancer." (PMID 26035356, 2015). "Based on these observations, MAPK15 may regulate c-Jun levels by increasing the phosphorylation and stability of c-Jun in gastric cancer cells." (PMID 26035356, 2015). "In addition, transient transfection of MAPK15 into AGS gastric cancer cells with low copy number resulted in an increase of c-Jun phosphorylation and stability." (PMID 26035356, 2015). "We next analyzed the CNAs and mRNA levels of MAPK15 in another set of 48 fresh-frozen tumor and matched normal tissues and in 16 gastric cancer cell lines using qPCR to validate the aCGH results and understand the correlation between copy number of MAPK15 and its expression." (PMID 26035356, 2015). "We analyzed the expression of MAPK15 using immunohistochemistry in concurrent lesions of normal, adenoma, and carcinoma derived from 45 gastric cancer patients, to understand the role of MAPK15 in the development of gastric cancer." (PMID 26035356, 2015). "We also measured protein levels of MAPK15 in the 16 gastric cancer cell lines." (PMID 26035356, 2015). "Furthermore, we investigated MAPK15 protein levels in concurrent lesions of normal, adenoma and carcinoma tissues from gastric cancer patients." (PMID 26035356, 2015). "However, the role of MAPK15 on the development of gastric cancer remains to be elucidated." (PMID 26035356, 2015). "In conclusion, the findings from the present study suggested that MAPK15 copy number gains may occur at a premalignant stage of gastric cancer and contribute to malignant transformation of gastric mucosa by increasing the phosphorylation and stability of c-Jun." (PMID 26035356, 2015). "Although there is no report on the mutation of MAPK15 in gastric cancer to date, our data suggest that MAPK15 overexpression may result from copy number gains as well as other molecular alterations in gastric cancer." (PMID 26035356, 2015). "In addition, MAPK15 overexpression in premalignant gastric lesion may be a predictive biomarker for the progression to invasive gastric cancer." (PMID 26035356, 2015). "Mitogen-activated protein kinase 15 (MAPK15; ERK8; ERK7) is the last identified member of the MAP kinase family, whose activity and overexpression have been recently correlated to transformation of human colon cancer cells and copy number gain in human gastric cancer, respectively." (PMID 26988910, 2016). "In this study, 17 samples showed high mRNA levels of MAPK15 without copy number alteration, suggesting that MAPK15 overexpression may result from other molecular alterations in addition to CNAs in gastric cancer." (PMID 26035356, 2015). "In this study, we found that MAPK15 promoted c-Jun phosphorylation independent of JNK, MEK1/2, and p38 in gastric cancer cells." (PMID 26035356, 2015).
lung carcinoma (8 papers, 2014 to 2024). "Elevated expression of MAPK15 is often seen across various types of cancer and cell lines, including lung cancer cells." (PMID 39329988, 2024). "This suggests that MAPK15 plays a key role in the metastasis of lung cancer cells, and MAPK15 can be used as a molecular marker for the early diagnosis or prognosis assessment of lung cancer." (PMID 36900191, 2023). "Analysis of changes in gene expression suggests that MAPK15 may serve as a biomarker to diagnose lung cancer at early stages and its prognostic assessment." (PMID 39329988, 2024). "At present, research about the function of MAPK15 is still limited, and its role in lung cancer metastasis remains unclear." (PMID 36900191, 2023). "Recently, our group has reported that MAPK15-mediated NF-κB activation enhances the arsenic trioxide-induced apoptosis through promoting the phosphorylation and degradation of IκBα, as well as the nuclear translocation of NF-κB in lung cancer cells." (PMID 38203280, 2023). "The insights provided by this study could facilitate understanding the role of MAPK15 in lung cancer progression and its potential modulatory role in cancer metastasis." (PMID 36900191, 2023). "The correlation between MAPK15 and lymph node metastasis in LUAD described here suggests that MAPK15 plays an important role in lung cancer development, which may lead to poor clinical outcomes." (PMID 36900191, 2023). "MAPK15 is highly expressed in human lung cancer cell lines and promotes the activation of NF-κB." (PMID 30524968, 2018). "Recently, our group has reported that MAPK15 can promote arsenic trioxide-induced apoptosis, as well as boosting the efficacy of combination therapy with cisplatin and TNF-α, in lung cancer cells." (PMID 36900191, 2023). "In this study, we reveal that knocking down EP3 can inhibit the migration of LUAD cells and that the expression of EP3 was positively regulated by MAPK15, which expands our understanding of EP3 and its regulation in lung cancer." (PMID 36900191, 2023). "Furthermore, we revealed the first time that MAPK15 promotes the expression of EP3 by interacting with p50, thereby enhancing the migration of lung cancer cells." (PMID 36900191, 2023). "Moreover, our group has reported the pivotal role of MAPK15 and NF-κB signaling in boosting the efficacy of combination therapy with cisplatin and TNF-α, as well as increasing arsenic trioxide-induced cell apoptosis, in lung cancer cell lines." (PMID 38203280, 2023). "RT-PCR and Western blot analyses have revealed relatively high MAPK15 expression in a few non-small cell lung cancer (NSCLC) lines; however, MAPK15 levels were found to be clearly detectable in lung biopsies of normal tissues but markedly lower in lung carcinomas, including one case of SCLC." (PMID 33138224, 2020).
breast carcinoma (5 papers, 2014 to 2025). "Decreased MAPK15 expression was observed in breast tumors, and loss of MAPK15 was related to breast cancer." (PMID 40746884, 2025). "In breast cancer, MAPK15 may play a role in maintaining tissue homeostasis through regulating the stability and activity of ERα, while the loss of MAPK15 expression is closely related to breast cancer progression." (PMID 38203280, 2023). "While YHWAB has a role in cell transformation, downregulation of MAPK15 (a proposed biomarker of breast cancer) increases cell motility in breast cancer and decreases apoptosis." (PMID 37367050, 2023).
colon cancer (5 papers, 2016 to 2023). "We have previously shown that MAPK15 promotes the transformation of colon cancer by mediating the activation of c-Jun." (PMID 36900191, 2023). "MAPK15-mediated c-Jun phosphorylation increases tumorigenesis of human colon cancer." (PMID 30524968, 2018).
chronic myeloid leukemia (4 papers, 2018 to 2025). "Afterward, MAPK15 regulates oncogene-dependent cell proliferation and the tumor formation of human chronic myeloid leukemia via physically recruiting the oncogene to autophagic vesicles." (PMID 38203280, 2023). "MAPK15 mediates the activation of autophagy through starvation, and may be a novel target for small molecule drugs with therapeutic effects in chronic myeloid leukemia." (PMID 40746884, 2025). "MAPK15 also mediates BCR-ABL1- induced autophagy and regulates oncogene-dependent cell proliferation and tumor formation in human chronic myeloid leukemia." (PMID 30524968, 2018).
male germ cell tumors (4 papers, 2016 to 2025). "The MAPK15 also promotes cell proliferation and protects against DNA damage in male germ cell tumors." (PMID 39866235, 2025). "The up-regulation of MAPK15 reportedly prevents DNA damage in male germ cell tumors." (PMID 30524968, 2018). "Indeed, the more aggressive phenotype granted by MAPK15 overexpression to NTera2/D1 cells nicely fits with the evidence that MAKP15 levels positively correlate to germ cell tumor malignancy in patients, being this kinase downregulated in the more benign teratomas and upregulated in the malignant EC." (PMID 26988910, 2016). "In addition, mitogen-activated protein kinase 15 (MAPK15), the last identified member of the MAP kinase family, play an important role in promoting cell proliferation and preventing DNA damage in male germ cell tumors." (PMID 29416701, 2018). "Interestingly, whereas MAPK15 was moderately overexpressed in all pure seminomas, the analysis of non-seminomatous germ cell tumors revealed a more complex expression pattern." (PMID 26988910, 2016).
colorectal cancer (3 papers, 2015 to 2025). A primary or metastatic malignant neoplasm that affects the colon or rectum. "While no in vivo MAPK15 substrates have been identified thus far, overexpression of MAPK15 is known to increase the transactivation of activator-proteins-1 by phosphorylating c-Jun at Ser63 and Ser73 in colorectal cancer cells." (PMID 26035356, 2015). "Interestingly, data from the literature indicate that, in gastric and colorectal cancer cells, MAPK15 can directly phosphorylate JUN on Ser63/73." (PMID 40507959, 2025). "In T cells isolated from colorectal cancer, we have a similar pattern: The percentage of T cells expressing ERK3/MAPK6 and NLK is higher than the percentage of T cells expressing ERK4 (MAPK4) and ERK7/8 (MAPK15)." (PMID 39348153, 2025).
lung adenocarcinoma (3 papers, 2023 to 2025). A carcinoma that arises from the lung and is characterized by the presence of malignant glandular epithelial cells. "MAPK15 is associated with lymph node metastasis and stimulates lung adenocarcinoma cell movement through prostaglandin E2 receptor and NF-κB p50 signaling." (PMID 39866235, 2025). "This study found that MAPK15 is highly expressed in the tissues of patients with lung adenocarcinoma lymph node metastasis, and MAPK15 interacts with p50 to regulate the expression of EP3 at the transcriptional level, thereby promoting cancer cell migration." (PMID 36900191, 2023). "Our previous study showed that MAPK15 is required for distant metastasis in lung adenocarcinoma through regulating EP3." (PMID 38203280, 2023). "More recently, we clarify that MAPK15 interacts with NF-κB p50 and enters the nucleus, in which NF-κB p50 binds to the EP3 promoter and transcriptionally regulates the expression of EP3, thereby affecting the migration of lung adenocarcinoma." (PMID 38203280, 2023).